RN7SKP186 (RN7SK pseudogene 186)
Synonyms: RN7SKP138
Gene: Miscellaneous RNA gene on chromosome 6 (30,864,250 to 30,864,552, forward strand). Ensembl gene ENSG00000202241.
Homologues: Orthologues: chimpanzee 7SK (99% identical). Paralogues in human: RN7SKP9 (77% identical), RN7SKP180 (77% identical), RN7SKP50 (77% identical), 7SK (76% identical), RN7SKP255 (76% identical), RN7SKP90 (76% identical), RN7SKP71 (76% identical), RN7SKP124 (75% identical), RN7SKP184 (75% identical), RN7SKP189 (75% identical), RN7SKP203 (75% identical), RN7SKP78 (75% identical), and 284 more.